NAT1 (N-acetyltransferase 1)
Diseases named in the same sentence as NAT1 in open-access papers (continued):
Sharing a sentence is not in itself a finding about the gene and the disease.
breast carcinoma (continued). "Analysis of data from the TCGA database indicated that the expression of NAT1 mRNA was markedly decreased in COAD, kidney chromophobe, and rectum adenocarcinoma tissues compared with the corresponding normal tissues, but increased in those of breast cancer (P < 0.05)." (PMID 31781164, 2019). "The present study suggests that NAT1 may not be a good marker of ER positive breast cancer, especially when its level of expression is low." (PMID 29969986, 2018). "In addition, we found that breast cancer patients with tumors expressing NAT1 tended to have better overall survival than those whose tumors were NAT1-negative." (PMID 25528056, 2014). "The selective expression of NAT1 in tumor subtypes is not confined to breast cancer." (PMID 21347396, 2011).
colorectal cancer (11 papers, 1998 to 2024). A primary or metastatic malignant neoplasm that affects the colon or rectum. "NAT1 alleles NAT1*4 (0.98) and NAT1*15 (0.02) were present at a similar frequency in patients with colorectal cancer (n=260) and in a Scottish control group (n=323)." (PMID 9528834, 1998). "The third allele, NAT1*14, was present only in the colorectal cancer group at a frequency of 0.006." (PMID 9528834, 1998). "We detected two NAT1 polymorphisms in colorectal cancer patients by heteroduplex analysis." (PMID 9528834, 1998). "In conclusion, the results demonstrate that NAT1 plays a significant role in inhibiting the epithelial-mesenchymal transition (EMT) of colorectal cancer." (PMID 38916406, 2024). "We detected NAT1 expression in four colorectal cancer cell lines by qPCR and WB, and found that NAT1 expression was low in HCT116 cell line and high in SW480 cell line." (PMID 38916406, 2024). "To further investigate the role of NAT1 in liver metastasis, we established a mouse liver metastasis model of colorectal cancer cells injected into the spleen." (PMID 38916406, 2024). "The expression of NAT1 is low in cancer tissues, and there are differences in the expression of NAT1 in different stages of colorectal cancer." (PMID 38916406, 2024). "This further verified that NAT1 inhibits VEGF expression by regulating the glycolysis ability of colorectal cancer cells." (PMID 38916406, 2024). "Experimental results indicated that NAT1 inhibited the glycolysis of colorectal cancer cells, consequently inhibiting the occurrence of liver metastasis." (PMID 38916406, 2024). "The role and molecular mechanism of NAT1 on tumor cells were verified by establishing a cell model of overexpression and knockdown of NAT1, and further verified by establishing a liver metastasis model of colorectal cancer for animal experiments." (PMID 38916406, 2024). "Our findings indicate that overexpressing NAT1 in colorectal cancer cells can inhibit the glycolytic capacity of these cells, consequently suppressing the expression of VEGF and affecting the formation of liver metastases." (PMID 38916406, 2024). "The expression of NAT1 is also different in different stages of colorectal cancer, and the higher the stage, the lower the expression of NAT1." (PMID 38916406, 2024). "In vivo and in vitro experiments have demonstrated that overexpression of NAT1 reduces the ability of metastasis and invasion of colorectal cancer cells." (PMID 38916406, 2024). "NAT1 (N-acetyltransferase 1) plays a crucial role in the invasive and metastatic processes of colorectal cancer." (PMID 38916406, 2024). "Our study will further clarify the role of NAT1 in colorectal cancer and how to regulate the occurrence of liver metastasis in colorectal cancer." (PMID 38916406, 2024). "NAT1 plays an important role in various cancers, but there are few studies on the specific mechanism of NAT1 in colorectal cancer, especially in the mechanism of liver metastasis in colorectal cancer." (PMID 38916406, 2024). "Cai Jiaqin &’s research found that the expression of NAT1 was significantly reduced in colorectal cancer, which was independently related to the poor prognosis of colorectal cancer patients." (PMID 37626132, 2023). "By contrast, NAT1 expression in ovarian, prostate, cervical and colorectal cancers showed single, normally-distributed populations." (PMID 29969986, 2018). "Therefore, our study highlights the importance of NAT1 in liver metastasis of colorectal cancer and suggests that NAT1 can be used as a potential prognostic marker and therapeutic target to improve the clinical treatment of metastatic colorectal cancer." (PMID 38916406, 2024). "Therefore, increased NAT1 levels can inhibit the invasion and migration of colorectal cancer cells by affecting EMT." (PMID 38916406, 2024). "Of course, in addition to the PI3K/AKT/mTOR pathway, other pathways may also exist in NAT1 interactions to regulate colorectal cancer glycolysis." (PMID 38916406, 2024).
colorectal cancer (continued). "RNA sequencing data suggests that NAT1 may regulate liver metastasis of colorectal cancer through the PI3K/AKT/mTOR signaling pathway and inhibits the expression of glycolytic-related metabolic enzymes such as GLUT1 and LDHA." (PMID 38916406, 2024). "Therefore, the objective of this study is to investigate the impact of NAT1 on colorectal cancer metabolism and provide novel therapeutic insights and targets for the management of colorectal cancer." (PMID 38916406, 2024). "Additionally, NAT1 weakens the glycolytic ability of colorectal cancer cells by suppressing the expression of GLUT1 and LDHA." (PMID 38916406, 2024). "Based on this, we hypothesized that NAT1 might regulate liver metastasis by modulating the glycolytic capacity of colorectal cancer cells." (PMID 38916406, 2024). "Similarly, it was reported that NAT1 mRNA was reduced in colorectal carcinoma compared with normal tissues, while the methylation of the promoter region of NAT1 was higher in colorectal carcinoma than that in normal tissues." (PMID 35111813, 2021). "Stratified analysis of the NAT1, NAT2 genotype on colorectal cancer and adenoma risk." (PMID 22905173, 2012). "There have been an increasing number of studies with evidence suggesting that the N-acetyltransferase 1 (NAT1) and N-acetyltransferase 2 (NAT2) genotypes may be implicated in the development of colorectal cancer (CRC) and colorectal adenoma (CRA)." (PMID 22905173, 2012). "Thus, the genotypes of NAT1 and NAT2 coding for the rapid acetylator phenotype carry a higher risk for colorectal cancer." (PMID 16827944, 2006). "We conclude that polymorphisms within the coding region of the NAT1 gene are infrequent and do not appear to have an independent association with colorectal cancer risk." (PMID 9528834, 1998). "Low expression of NAT1 may promote liver metastasis of colorectal cancer." (PMID 38916406, 2024). "NAT1 and NAT2 are two members of the N-acetyltransferases (NAT) family that encode polymorphic enzymes catalyzing the metabolic activation of heterocyclic aromatic amines (HCAs), which have been considered established carcinogens in human colorectal cancer and urinary bladder cancer." (PMID 34322151, 2021). "While NAT1 expression is generally low in colorectal cancer, its role in liver metastasis of colorectal cancer has not been extensively studied." (PMID 38916406, 2024). "Our findings highlight that overexpression of NAT1 significantly inhibits the PI3K/AKT/mTOR signaling pathway, thereby suppressing EMT, glycolytic ability, and VEGF expression in colorectal cancer cells, collectively preventing the development of liver metastasis." (PMID 38916406, 2024). "Therefore, it can be inferred that NAT1 suppresses liver metastasis of colorectal cancer by modulating EMT and glycolysis in colorectal cancer cells through the PI3K/AKT/mTOR signaling pathway." (PMID 38916406, 2024). "NAT1 exhibits higher expression in brain cancer tissues than that in normal tissue, whereas NAT1 expression was significantly less in colorectal cancer tissues than that in normal tissues and adjacent non-cancerous tissues." (PMID 32793479, 2020).
bladder cancer (9 papers, 1999 to 2024). "The phenotype of one of the most common NAT1 variants (NAT1*14B) is substrate-dependent and is associated with smoking-induced lung cancer and urinary bladder cancer." (PMID 39766269, 2024). "In contrast, higher activity NAT1 alleles such as NAT1*10 are associated with lower prevalence of urinary bladder cancer." (PMID 35273499, 2022). "Our current hospital-based case-control study particularly seeks to investigate the potential association of NAT1 genetic polymorphism and bladder cancer among Lebanese men residing in Lebanon." (PMID 22956951, 2012). "This study investigates a possible association between N-acetyltransferase 1 (NAT1) genotype, a drug-metabolizing enzyme coding gene, and bladder cancer in Lebanese men." (PMID 22956951, 2012). "Larger epidemiological studies are required to clarify the relationship between bladder cancer risk and the NAT1*10 allele." (PMID 17026750, 2006). "Urinary bladder cancer is most frequently associated with NAT1 genetic polymorphism." (PMID 35273499, 2022). "Also, we have included NAT1*14B allele which is an important variant associated with lung and urinary bladder cancer." (PMID 36386142, 2022). "Also, a recent study reported that individuals carrying NAT1*14B developed urinary bladder cancer with higher muscle-invasiveness and higher tumor grade compared to individuals with reference NAT1*4 suggesting the importance of NAT1*14B in cancer risk studies." (PMID 36386142, 2022). "Because of the relatively high frequency of NAT1*14A in the Lebanese population, the attributable risk of bladder cancer in this population may be high." (PMID 22956951, 2012). "Studies also suggest that NAT1*10 genetic variant may be associated with elevated levels of NAT1 enzyme activity and was reported to be associated with colon cancer, and to be less frequent among studied groups of bladder cancer patients." (PMID 22956951, 2012). "Our results suggest that NAT1*14A influences bladder cancer risk in Lebanese males." (PMID 22956951, 2012). "Furthermore, we did not observe any statistically significant effect modification by cigarette smoking status for the NAT2 or NAT1 genotypes and bladder cancer risk (p for interaction > 0.4)." (PMID 17026750, 2006). "NAT1 polymorphisms may also affect individual bladder cancer risk by interacting with cigarette smoking." (PMID 17026750, 2006). "It was reported that partial linkage disequilibrium exists between the NAT1*10 allele and the NAT2 fast acetylation genotype, and a reduced risk for bladder cancer was identified in carriers of these co-existing genotypes." (PMID 25413361, 2014). "Given their biological role, polymorphisms within the GSTT1, GSTM1, NAT1, and NAT2 genes may be important in determining an individual's susceptibility to bladder cancer." (PMID 17026750, 2006). "Our findings do not support an association between the NAT1 polymorphisms, cigarette smoking, and bladder cancer; however we had little power to detect such an association." (PMID 17026750, 2006). "The results are consistent with the hypothesis that NAT1 and NAT2 might modulate the susceptibility to bladder cancer associated with cigarette smoking." (PMID 10507782, 1999). "We compared the distributions of the GSTM1, GSTT1, NAT1, and NAT2 genotypes between incident and prevalent bladder cancer cases in men and women separately to determine whether the variant alleles were associated with survival." (PMID 17026750, 2006).
breast tumor (9 papers, 2007 to 2021). "Human NAT1 is highly over-expressed in estrogen receptor positive breast tumours and is implicated in susceptibility to neural tube defects." (PMID 17961509, 2007). "NAT1 mRNA is also elevated in male breast cancer and breast tumors that preferentially metastasize to the bone." (PMID 29969986, 2018). "Studies using human breast tumour-derived cell lines have indicated a 50-fold range of (HUMAN)NAT1 activities among estrogen-receptor (ER)-positive cell lines, the highest activity being observed in the ZR-75-1 line." (PMID 24823794, 2014). "Particular attention has been paid to the small molecule naphthoquinone 1 because of its striking selectivity for (HUMAN)NAT1/(MOUSE)NAT2 and its diagnostic/prognostic potential in ER-positive breast tumours." (PMID 24823794, 2014). "Previous studies have shown that NAT1 expression is increased in breast tumors compared to normal breast tissue." (PMID 19352457, 2009). "Altered expression of the human orthologue in breast tumours, in which there is endocrine signalling, suggests that human NAT1 should be considered as a potential biomarker for neuroendocrine tissues and tumours." (PMID 17896208, 2008). "Recent studies linking levels of NAT1 expression with those of the estrogen receptor in breast tumour tissue indicate that the role of NAT1 in carcinogenesis and tumour growth in some tissues relates to endogenous as opposed to xenobiotic metabolism." (PMID 17961509, 2007). "In particular, since the expression of (HUMAN)NAT1 is related to the development and progression of oestrogen-receptor-positive breast cancer, these structure-based tools will facilitate the ongoing design of candidate compounds for use in (HUMAN)NAT1-positive breast tumours." (PMID 25432241, 2014).
colon carcinoma (8 papers, 2012 to 2022). "SLC6A2, also known as NAT1, has been found to be prognostic for colon cancer, and both in vivo and in vitro studies have linked expression to survival in many cancer types, including prostate and breast." (PMID 36199081, 2022). "Inhibition of NAT1 expression in colon carcinoma HT-29 and prostate carcinoma cells 22Rv1 cells up-regulated e-cadherin, a marker of a more epithelial phenotype." (PMID 31910058, 2020). "NAT1 is located on the short arm of chromosome 8 (8p21), a region that is commonly deleted in colon cancer." (PMID 29518119, 2018). "Previously, it was reported that HT-29 colon cancer cells, which have a large deletion at 8p21-22, show marked morphological changes, increased E-cadherin expression and altered cell-cell contact inhibition following down-regulation of NAT1 with shRNA." (PMID 29518119, 2018). "For the top colon cancer MEGs, the consistent tumor suppressor genes included MAP2K4, MAPK10, RUNX3, WNK2 (the four genes were identified by the TSGene 2.0 database), BECN1, FASN, NAT1, and NR3C2." (PMID 33273919, 2020). "Moreover, knockdown of NAT1 expression using short-hairpin RNA (shRNA) in the noninvasive HT-29 colon cancer cell line resulted in a marked change in cell morphology that was accompanied by an increase in cell-cell contact inhibition of growth and a loss of cell viability at confluence." (PMID 25528056, 2014).
triple-negative breast carcinoma (7 papers, 2015 to 2023). An invasive breast carcinoma which is negative for expression of estrogen receptor (ER), progesterone receptor (PR), and human epidermal growth factor receptor 2 (HER2). "In a later study, the same group silenced NAT1 in the triple-negative breast cancer cell lines and tested the invasiveness of the cells in both in vitro and in vivo." (PMID 31531019, 2019). "We knocked down NAT1 using a lentivirus-based shRNA approach and observed marked changes in cell morphology in the triple-negative breast cancer cell lines MDA-MB-231, MDA-MB-436, and BT-549." (PMID 25627111, 2015). "Different studies demonstrated that the 3′-untranslated region of NAT1 is a direct target for miR-1290, and miR-6744-5p, where its expression is downregulated, promoting distant metastasis in triple-negative breast cancers." (PMID 35153780, 2022). "N-acetyltransferase 1 (NAT1) acts as a direct target of miR-6744-5p and promotes the Distant metastasis in triple-negative breast cancer." (PMID 34398900, 2021). "Taken together, the results show that NAT1 can alter the invasion and metastatic properties of some triple-negative breast cancer cells but not all." (PMID 25627111, 2015).
colon adenocarcinoma (4 papers, 2011 to 2023). "N-acetyltransferase 1 (NAT1) CpG sites methylation associated with overall survival in colon adenocarcinoma (COAD)." (PMID 31781164, 2019). "Survival analysis of N-acetyltransferase 1 (NAT1) CpG sites combine with mRNA expression in colon adenocarcinoma (COAD)." (PMID 31781164, 2019). "In this study, we sought to examine the prognostic value and clinical significance of NAT1 methylation in colon adenocarcinoma (COAD)." (PMID 31781164, 2019). "Association of N-acetyltransferase 1 (NAT1) mRNA and two CpG sites with clinicopathological features of colon adenocarcinoma (COAD)." (PMID 31781164, 2019). "HT-29 cells are derived from a human colon adenocarcinoma that has a large deletion at 8p21, the site of the NAT1 gene." (PMID 21347396, 2011). "In this study, we have knocked down NAT1 in the colon adenocarcinoma cell-line HT-29 and found a marked change in cell morphology that was accompanied by an increase in cell-cell contact growth inhibition and a loss of cell viability at confluence." (PMID 21347396, 2011). "For these studies, we chose the well-characterized human colon adenocarcinoma cell line HT-29 because these cells carry only one copy of the NAT1 gene due to a deletion at 8p21-22." (PMID 21347396, 2011). "Compared with tumor adjacent tissues, EEF1A2, PBK and TIMP1 showed significant upregulation in colon adenocarcinoma, while ATP2A3, CDC25C, MMP3 and NAT1 showed significant downregulation." (PMID 37626132, 2023).
asthma (3 papers, 2007 to 2020). "These curves indicate that in individuals carrying the NAT1 mutation, the risk of asthma increases approximately 2-fold or more in 20% of the possible polygenotypes present in a population of workers exposed to diisocyanates." (PMID 17384770, 2007). "Variation in the N-Acetyltransferase 1 (NAT1) gene modified asthma risk in children exposed to SHS." (PMID 32867076, 2020).
lung carcinoma (3 papers, 2006 to 2024). "In a subsequent study, the association of NAT1*14 alleles possessing 560G > A (rs4986782) (R187Q) with higher incidence of lung cancer nearly reached statistical significance while an inverse association with the NAT1*10 allele achieved statistical significance." (PMID 35273499, 2022).
spina bifida (3 papers, 2008 to 2025). A congenital neural tube defect in which vertebrae are not fully formed. "Several NAT1 variants are independently associated with increased risk for spina bifida, and one study examined potential interactions between these variants and maternal smoking." (PMID 40666233, 2025). "Accordingly, reduced NAT1 activity in humans has been related to a reduced risk of spina bifida, a condition well known to be associated with low levels of folates in pregnant mothers." (PMID 18773084, 2008). "The overexpression of the orthologue of human NAT1 in mouse embryos causes developmental abnormalities which are reminiscent of spina bifida-like phenotype." (PMID 18773084, 2008). "Rare loss-of-function mutations in (HUMAN)NAT1 are associated with reduced risk of spina bifida, and (HUMAN)NAT1 genotype has therefore been identified as a risk factor for this condition." (PMID 24823794, 2014).
glioma (2 papers, 2015 to 2022). A benign or malignant brain and spinal cord tumor that arises from glial cells (astrocytes, oligodendrocytes, ependymal cells). "Increased expression of each of NAT1, NAT2 and NAT10 correlated negatively with patient survival in the group of “all gliomas” patients." (PMID 26292663, 2015).
Insulin resistance (2 papers, 2021 to 2022). Increased resistance towards insulin, that is, diminished effectiveness of insulin in reducing blood glucose levels. "NAT2 is associated with insulin resistance, and deficiency of the mouse orthologue (i.e., NAT1) has also been associated with mitochondrial dysfunction." (PMID 35259281, 2022). "The target genes TRDMT1, ZNF418, NAT1, and CDC7 have been experimentally associated through their expression levels or through knockouts, or are used as biomarkers, for waist circumference, BMI, obesity, or insulin resistance." (PMID 33957961, 2021).